TNF (tumor necrosis factor)
Diseases named in the same sentence as TNF in open-access papers (continued):
Sharing a sentence is not in itself a finding about the gene and the disease.
meningoencephalitis (13 papers, 2012 to 2026). Inflammation of the meninges and brain, generally secondary to an infectious cause. "These lesions consisted of a meningoencephalitis with moderate to severe perivascular cuffing associated with the presence of NiV RNA, IL-6 and TNF mRNA." (PMID 40125323, 2025). "In the literature, there are a few case reports, series, and retrospective studies which have demonstrated the association of rheumatoid (aseptic) meningoencephalitis after starting tumor necrosis factor (TNF) inhibitors." (PMID 30652043, 2018). "Meningoencephalitis presumably caused by Enterovirus infection elicits robust intrathecal pro-inflammatory cytokine pattern, with statistically higher levels of IL-6, TNF and IL-17." (PMID 26286516, 2015). "The present results challenge this finding, since increased levels of TNF-α were found in the CSF of patients with meningoencephalitis." (PMID 26286516, 2015). "On the other hand, TNF-α/IL-10 and IL-17/IL-10 ratios were significantly lower in virus positive when compared to undiagnosed meningoencephalitis patients." (PMID 26286516, 2015). "In this regard, levels of interleukin-6 (IL-6) and tumor necrosis factor alpha (TNF-α) were measured in cerebrospinal fluids from patients with meningoencephalitis." (PMID 26286516, 2015). "The diad TNF-α/IL-17 is seen but exclusively in the network composed of data from undiagnosed meningoencephalitis patients with low cellularity." (PMID 26286516, 2015). "At last, network analysis revealed that the diad TNF-α/IL-17 axis is seen exclusively in the network composed of data from undiagnosed meningoencephalitis patients with low cellularity." (PMID 26286516, 2015). "In this respect, the evolved strain also resembled the neurotropic fungus C. neoformans, which likewise induces local TNFα and IL-6 responses in the brain, correlating with its presence in the CNS and the progression of meningoencephalitis." (PMID 25356907, 2014). "TNF-α was found as an important biomarker for identifying patients with undiagnosed meningoencephalitis with low cellularity, which is in agreement with recent reports that recommend the evaluation of TNF-α levels in the diagnosis of bacterial and meningoencephalitis." (PMID 26286516, 2015). "In addition, undiagnosed meningoencephalitis patients had higher values of the upper-left corner of the graph (high cytokine levels with low cellularity) for both TNF-α (39 %) and IL-17 (31 %) when compared to patients with virus-positive meningoencephalitis (TNF-α = 13 % and IL-17 = 5 %)." (PMID 26286516, 2015). "The frequency of patients with viral meningoencephalitis (TNF-α and IL-17 = 55 %) was higher in the high cellularity quarters (top and bottom right) of the 4-quarter graph when compared to frequency of patients with undiagnosed meningoencephalitis in those quarters (TNF-α and IL-17 = 37–38 %)." (PMID 26286516, 2015). "When the cytokine levels of patients with low cellularity were contrasted, patients with undiagnosed meningoencephalitis presented levels of TNF-α and IL17 statistically higher than patients with virus-positive meningoencephalitis." (PMID 26286516, 2015). "In the present research, we described histopathological changes, viral dissemination, glial reaction, and expression of TNFα, TGF-β, INF-γ, IL-6, IL-10, IL-12p40, IL-12p70, MCP-1, and NO in the brains of young adult mice after Maraba virus-induced meningoencephalitis." (PMID 32294697, 2020). "BDV-infection of TNF-transgenic mice resulted in non-purulent meningoencephalitis accompanied by epileptic seizures with a higher frequency in homozygous animals." (PMID 22848506, 2012). "In contrast, in both TNF-overexpressing transgenic mice groups a progressive severe non-purulent meningoencephalitis with astrogliosis and activation of microglia was noted; only astrocytes were activated in the wild-type mice." (PMID 22848506, 2012).
meningoencephalitis (continued). "After nasal exposure of susceptible end hosts, BoDV1 primarily spreads to the limbic system, and eventually to the entire central nervous system (CNS), resulting in the release of pro-inflammatory cytokines like TNF, interleukin (IL)-1, and IL-2, followed by severe non-purulent meningoencephalitis." (PMID 38339126, 2024). "In this regard, several ratios between cytokines were altered such as IFN-γ/IL-10, IFN-γ/TNF-α and IFN-γ/IL-17 (data not shown) in patients with meningoencephalitis." (PMID 26286516, 2015).
narcolepsy (13 papers, 2008 to 2024). A sleep disorder characterized by a tendency for excessive sleepiness during the day which occurs even after adequate sleep in the nighttime. "Indirect support for an involvement of cytokines in the pathophysiology of narcolepsy comes from a number of molecular genetic studies, including one of our own group in which variants of TNF were associated with narcolepsy." (PMID 18714344, 2008). "Furthermore, polymorphisms in the TNF-promoter gene have been proposed as a possible cause of increased TNF-secretion in narcolepsy patients." (PMID 36358399, 2022). "Extended daytime sleepiness elevates IL-6 and TNF-, which suggests that a disrupted sleep–wake cycle modulates cytokine profile in narcolepsy patients." (PMID 36358399, 2022). "One possible hypothesis would be that the activation of the TNF-α system and a sTNF-R p75-mediated activation of cells of the immune system would lead to an autoimmune destruction of hypocretin neurons, which seems to be strongly associated with the development of narcolepsy." (PMID 19506720, 2008). "Increased serum TNF-a levels were found in narcolepsy patients." (PMID 38771396, 2024). "TNF injections into the brain stimulate NREM sleep while inhibiting spontaneous sleep, which could explain EDS in narcolepsy patients." (PMID 36358399, 2022).
nonalcoholic fatty liver (13 papers, 2015 to 2025). "Excessive mitochondrial ROS exacerbates mitochondrial dysfunction and can also activate NF-κB and promote tumor necrosis factor α (TNF-α), interleukin (IL)-1β, and IL-6 production and induce liver inflammation and the development of nonalcoholic fatty liver." (PMID 36678243, 2023). "TNF-α and IL-6 inhibit the expression of adiponectin and promotes the inflammatory response of nonalcoholic fatty liver." (PMID 31717842, 2019). "Although, the production of TNF-α may be an early event during the course of nonalcoholic fatty liver (NAFL), TNF-α may play a more substantial role in the pathogenesis of nonalcoholic steatohepatitis (NASH) and NAFLD-associated fibrosis." (PMID 37407724, 2023). "Notably, a distinct subset of resident CXCR6+ PD1+ TNF+ CD8+ T cells was discovered, which is assumed to play an important role in the transition of simple steatosis (nonalcoholic fatty liver; NAFL) to NASH and HCC." (PMID 37958479, 2023).
pheochromocytoma (13 papers, 2010 to 2025). "Tumors that have been reported to cause NICTH include malignancies associated with insulin receptor antibodies, tumor necrosis factor (TNF), interleukin (IL) -1 or -6; pheochromocytoma associated with excess catecholamine production; and paraneoplastic production of IGF-1 or IGF-2." (PMID 24934576, 2014). "Studies showed that pheochromocytoma tumors can secrete hormones other than catecholamines, including cytokines, mainly interleukin (IL)-1, IL-6, and tumor necrosis factor alpha (TNF-α)." (PMID 41477390, 2025). "MALAT1 was also proven to upregulate pro-inflammatory factors in poststroke mice, and MALAT1 knockdown partially reduced the levels of TNF-α, IL-6, and IL-1β in mouse pheochromocytoma cell lines after oxygen and glucose deprivation/reperfusion." (PMID 40869277, 2025). "Peripheral CD14+ monocytes isolated from patients with pheochromocytoma/paraganglioma exhibit upregulated proinflammatory genes and increased H3K4me3 on TNF and IL1B promoters." (PMID 41028520, 2025). "An earlier study has shown that the uptake and degradation of phagocytosed apoptotic pheochromocytoma 12 cells by primary neonatal microglia increased upon their activation with LPS and TNF-α." (PMID 36829517, 2023). "Pheochromocytomas are able to produce a variety of biologically active neuropeptides, hormones other than catecholamines, and cytokines, mainly IL-1, IL-6, and TNF-α." (PMID 27579040, 2016). "Additionally, pheochromocytoma cells are immune to death receptor ligands so alternate use of TNF-α and TRAIL was justified with regard to cell viability, APP processing, and molecular markers of autophagy." (PMID 25821818, 2015). "NICTH has also been reported in conjunction with paraneoplastic production of insulin receptor antibodies, tumor necrosis factor (TNF), interleukin (IL) -1 and -6, catecholamine (pheochromocytoma) and IGF-1." (PMID 24934576, 2014). "In addition, serum IL-6 (78.8 pg/mL [normal range < 4]) was elevated, while IL-1β (10 pg/mL) and tumor necrosis factor-alpha (TNF-α; 1.17 pg/mL) levels were normal, which led us to diagnose an IL-6-producing pheochromocytoma." (PMID 34117557, 2021). "Tyrosine hydroxylase is induced by EGFR as shown in clonal pheochromocytoma cell line; its overexpression leads to decreased interferon (IFN)-γ and tumor necrosis factor (TNF) levels as shown for lymphocytes, which could be a marker for poor prognosis, and activates the xc(-) system." (PMID 34687436, 2022).
respiratory distress syndrome (13 papers, 2013 to 2024). "Therefore, this study aims to establish a correlation between plasma levels of IGF1 and TNF-alpha in predicting the risk of developing ROP in premature neonates with respiratory distress syndrome treated with various modalities of respiratory support." (PMID 39194926, 2024). "In vitro studies demonstrate marked inhibitory effects of TNF-α on the expression of pulmonary surfactant proteins, SP-A and SP-B, and thus support the concept that TNF-α may contribute in the pathogenesis of respiratory distress syndrome, which often precedes BPD development." (PMID 33117383, 2020). "Tracheal aspirate levels of pro-inflammatory cytokines such as IL-6, IL-1β, TNF-α, and chemokines CCL2, CCL7, CCL8, and IL-8 (CXCL8) are higher in premature infants with respiratory distress syndrome who develop BPD." (PMID 33117383, 2020).
sinusitis (13 papers, 2009 to 2025). An acute or chronic inflammatory process affecting the mucous membranes of any sinus cavity. "It seems reasonable that LMWH can greatly reduce the inflammatory state of acute sinusitis, which causes the large-scale release of cytokines IL-6 and TNF-α." (PMID 34867331, 2021). "Our data demonstrated that serum levels of IL-6 and TNF-α were significantly increased in nasal packing-induced acute sinusitis rats, which were mainly Th1-related cytokines, and consistent with the pathogenic mechanism of acute sinusitis." (PMID 34867331, 2021). "Xin-Yi-Qing-Fei-Tang can reduce the nasal colonization of Streptococcus pneumonia, which causes sinusitis and increases tumor necrosis factor-alpha (TNF-α), interleukin-1 beta (IL-1β), interleukin-6 (IL-6), and monocyte chemotactic protein-1 (MCP-1) levels and the migration of macrophages." (PMID 33204289, 2020). "Furthermore, we investigated the nasal colonization of S. pyogenes, determined cytokine (TNF-α, IL-1β, and IL-6) levels, and conducted a splenocyte proliferative assay in a murine sinusitis model." (PMID 29853978, 2018). "However, he was being treated for sinusitis and it is possible that there was an increased release of inflammatory cytokines, TNF-α and ILs." (PMID 26861488, 2016).
Skin rash (13 papers, 2005 to 2024). A red eruption of the skin. "Some potential biomarkers of toxicity during TKI therapy include circulating cytokines, such as IL-6 and TNF-alpha, which have been associated with inflammatory side effects like skin rashes, gastrointestinal disturbances, and fatigue." (PMID 39882443, 2024). "Side effects of anti-TNF-α inhibitor therapy occurred in around 45% of patients, most frequently skin rashes (12.3%)." (PMID 36304532, 2022). "Patient 2 had partial responses to colchicine, but recurrence of rash, fatigue, and systemic inflammation led to empiric treatment with the TNF inhibitor etanercept at the age of 14, which rapidly improved skin rashes, normalized acute phase reactants, and led to long-term remission." (PMID 36932076, 2023). "TNF-α inhibitors have less of an effect on improving skin lesions than on musculoskeletal manifestation, and they may even aggravate skin rash." (PMID 36983699, 2023). "Cytokines sIL-2R and TNF-α increased in all 9 pediatric patients with the appearance of exanthema." (PMID 26315105, 2015). "Thus, the role of tumor necrosis factor-α (TNF-α) and interleukin-1 (IL-1) in the development of EGFR inhibitor-associated skin rash was shown and a possible therapeutic role for anti-TNF agents was suggested." (PMID 22761877, 2012).
skin reaction (13 papers, 2009 to 2025). "Certolizumab pegol, a TNF inhibitor, is generally well-tolerated but has been rarely associated with skin reactions, mostly in the category of leukocytoclastic vasculitis." (PMID 41158918, 2025). "TNF-inhibitors and older biologic agents, such as infliximab or adalimumab, are often associated with paradoxical skin reactions (category 4)." (PMID 37685662, 2023). "TNF-alpha inhibitors, such as adalimumab, etanercept, infliximab, certolizumab pegol, and golimumab, are widely used to manage inflammatory diseases, yet they have been associated with unexpected skin reactions, including the emergence of new lesions or changes in pre-existing conditions." (PMID 40141829, 2025). "In contrast to anti-TNF inhibitors, ustekinumab treatment results in a much lower rate of adverse skin reactions and can even resolve them after switching from another drug." (PMID 36584073, 2022). "The three cytokines TNF-α, iNOS and TGF-β detected by immunohistochemistry showed a significant association with the presence of skin reaction." (PMID 22180790, 2011). "Excluding the injection site skin reactions, which were frequent in patients treated with IL-1 inhibitors, anti-TNF agents accounted for the treatment approach more frequently burdened by a higher frequency of adverse events overall, especially infectious adverse events." (PMID 40046741, 2025). "Together with IL-1 beta and TNF-alpha, it is involved in inflammatory skin reactions." (PMID 39201678, 2024). "However, patients receiving these biological agents frequently experience paradoxical skin reactions (PSRs), particularly with anti-TNF-α treatments." (PMID 39469389, 2024). "Levels of all the antibodies tested and TNF α were lowest in patients with only skin reaction." (PMID 21408123, 2011). "However, these agents may induce paradoxical skin reactions (PSRs), which are new or exacerbated immune-mediated skin disorders triggered by the targeted treatment, especially with anti-TNF-α agents." (PMID 39469389, 2024). "Paradoxical skin reactions were reported in patients treated with TNF inhibitors, but no serious adverse events were recorded." (PMID 38151265, 2023). "Luteolin and quercetin may be the core active ingredients of QYSLS in the treatment of EGFRI-related adverse skin reactions, and their therapeutic effects are potentially mediated through PTGS2, CCL2, and MMP9 in the IL-17 and TNF signaling pathway." (PMID 35372072, 2022). "It is worth noting that none of the patients in our cohort developed an adverse skin reaction and that 5 out of the 9 patients who provided skin swabs have a history of anti-TNF treatment." (PMID 36584073, 2022).
varicocele (13 papers, 2016 to 2025). A condition characterized by the dilated tortuous veins of the spermatic cord with a marked left-sided predominance. "According to the study, there is a significant upregulation in miR-155 in infertile men with varicocele or inflammatory conditions, and this is positively correlated with pro-inflammatory cytokines such as Tumor Necrosis Factor α (TNF-α)." (PMID 41283253, 2025). "Studies show that varicocele stimulates the release of proinflammatory and inflammatory cytokines such as interleukin-1 (IL-1), IL-6, IL-8, and tumor necrosis factor-alpha (TNF-α)." (PMID 37476898, 2023). "The potential correlation between the expression of YIPF and the testicular inflammatory response, as well as the fluctuation in TNF expression level induced by varicocele, has been suggested." (PMID 38136796, 2023). "In varicocele, both high levels and marked positivity of TNF-α were demonstrated with ELISA assessment and immunohistochemical staining." (PMID 36555779, 2022). "Among the other cytokines involved in the testicular tissue during varicocele, IL-6 and tumor necrosis factor-α (TNF-α) play an important pro-inflammatory role." (PMID 36555779, 2022). "MAS promotes spermatogenesis in varicocele-induced SD rat, probably by decreasing cytokines (IL-6, TNF-α) levels, regulating abnormal sex hormones, and decreasing oxidative stress, ER stress, and apoptosis." (PMID 31771569, 2019). "MAS promotes spermatogenesis in varicocele-induced SD rat, probably by decreasing cytokine (interleukin- 6, and TNF-α) levels, regulating abnormal sex hormones, and decreasing oxidative stress, ER stress and apoptosis." (PMID 31771569, 2019). "With respect to controls, the leucocytospermia and varicocele groups showed significantly increased sperm apoptosis (P = 0.009 and P = 0.011, respectively), IL-6 (P = 0.0001 and P = 0.004, respectively), and TNF-α(P = 0.0001 and P = 0.002, respectively) levels." (PMID 31781347, 2019). "Thirdly, MOP-induced downregulation of TGF-β3 and TNF-α may relate to the fact that MOP can decrease the inflammatory reaction caused by testicular hypoxia and the increased testicular temperature in the varicocele rat testis." (PMID 28090212, 2016). "The specific mechanism by which MOP decreases the level of cytokines (TGF-β3 and TNF-α) and increases the T level in varicocele testicular tissue remains unknown and further studies are warranted to elucidate this mechanism." (PMID 28090212, 2016). "In summary, we conclude that MOP promotes spermatogenesis and counteracts the varicocele-induced damage to the seminiferous epithelium and TJ, probably via decreasing cytokines (TGF-β3 and TNF-α) levels and regulating the abnormal sex hormones levels in experimental varicocele rats." (PMID 28090212, 2016). "As a result, we believe that TGF-β3 and TNF-α might be involved in the downregulation of TJ proteins, Occludin, Claudin-11, and ZO-1, and in the damage of the TJ structure that occurred in experimental varicocele." (PMID 28090212, 2016). "In our study, varicocele increased TGF-β3 and TNF-α levels in the left testicular tissue." (PMID 28090212, 2016). "A recent review highlighted that numerous varicocele-related studies involving both animal models and human patients, consistently reported an abnormal increase in the levels of pro-inflammatory cytokines, including IL1 and TNF-α, within seminal plasma, testicular tissue, and peripheral blood." (PMID 37589002, 2023). "MAS treatment of varicocele-induced group significantly decreased the levels of serum luteinizing hormone (LH) and follicle-stimulating hormone (FSH), as well as testicular interleukin-6 (IL6), tumor necrosis factor-α (TNF-α), ROS/RNS, and malondialdehyde (MDA)." (PMID 31771569, 2019).